NEK2 (NIMA related kinase 2)
Diseases named in the same sentence as NEK2 in open-access papers (continued):
Sharing a sentence is not in itself a finding about the gene and the disease.
liver cancer (11 papers, 2019 to 2026). An epithelial or non-epithelial malignant neoplasm that arises from the liver. "Preparing an anti-NEK2 monoclonal antibody (mAb) and using an mAb to establish an enzyme-linked immunosorbent assay (ELISA) kit can be applied in the detection of liver cancer in the population and improve the detection rate of liver cancer, especially in high-risk populations." (PMID 34706700, 2021). "The NEK2 gene has been identified as a tumor suppressor gene in breast, thyroid, gastric, and hepatic cancer." (PMID 37627077, 2023). "Taken together, our results suggest TOP2A, RRM2, NEK2, CDK1, and CCNB1 as HCC-associated hub genes that can serve as potential prognostic biomarkers in liver cancer." (PMID 34681056, 2021). "In this sense, it is important to develop sensitive monoclonal antibodies against NEK2 for the diagnosis of liver cancer." (PMID 34706700, 2021). "Taken together, our results strongly indicated that liver cancer patients with an upregulated level of TOP2A, RRM2, NEK2, CDK1, and CCNB1 were associated with poor prognosis." (PMID 34681056, 2021). "NEK2 has been well studied in liver cancer, with more than 30 publications on the subject." (PMID 40076620, 2025). "This hypothesis suggests that anti-NEK2 mAb has a potential tumor suppressive effect on liver cancer with high expression of NEK2 protein." (PMID 34706700, 2021). "Our previous study found that NEK2 was highly expressed in liver cancer cells and tissues, and the overexpression of NEK2 was related to clinicopathological features and poor prognosis of patients, suggesting that NEK2 may be an important biomarker of HCC." (PMID 34706700, 2021). "Subsequently, many studies reported that NEK2 was highly expressed in a variety of malignant tumors, such as liver cancer, gastric cancer, head and neck squamous cell carcinoma, and bladder cancer and was related to the occurrence and malignant transformation of tumors." (PMID 34706700, 2021). "Targeted inhibition of the NEK2 protein can effectively inhibit the growth of liver cancer cells." (PMID 34706700, 2021). "An anti-NEK2 mAb with high potency, high affinity and high specificity was prepared by prokaryotic expression system in this study and may be used in the establishment of ELISA detection kits and targeted treatment of liver cancer." (PMID 34706700, 2021). "Subsequent validation suggested TOP2A, RRM2, NEK2, CDK1, and CCNB1 as the prognostic biomarkers of liver cancer." (PMID 34681056, 2021). "Our results suggest the potential use of TOP2A, RRM2, NEK2, CDK1, and CCNB1 as prognostic biomarkers in liver cancer." (PMID 34681056, 2021). "Therefore, anti-NEK2 mAb may be a potential effective method of targeted therapy for liver cancer." (PMID 34706700, 2021). "Notably, high expression of Nek2 in HCC was significantly correlated with alpha-fetoprotein (AFP, P = 0.028), tumor size (P = 0.02), Barcelona Clinic Liver Cancer stage (BCLC stage, P = 0.031), and local relapse (P = 0.034)." (PMID 31319849, 2019). "Interestingly, three of them (CCNB1, TOP2A, NEK2) were also identified as crucial genes in HCV-HCC, which might to some extent reflect the common transcriptome regulatory mechanisms in liver cancer induced by viral hepatitis." (PMID 33946043, 2021). "The results revealed DNA topoisomerase II alpha (TOP2A), ribonucleotide reductase regulatory subunit M2 (RRM2), never in mitosis-related kinase 2 (NEK2), cyclin-dependent kinase 1 (CDK1), and cyclin B1 (CCNB1) as the hub genes for liver cancer." (PMID 34681056, 2021).
lung adenocarcinoma (11 papers, 2008 to 2024). A carcinoma that arises from the lung and is characterized by the presence of malignant glandular epithelial cells. "Although previous studies have indicated that the NEK2 gene is involved in lung adenocarcinoma and that non-small cell lung cancers overexpress NEK2 protein, its expression in SCLC and other BP-NENs has not been studied so far." (PMID 32504181, 2020). "In addition, NEK2 overexpression was enhanced in advanced lung adenocarcinoma, suggesting a role for NEK2 in tumor progression." (PMID 34712733, 2021). "In terms of overall survival, patients with high NEK2 expression in NSCLC and its subtypes of lung adenocarcinoma have a poor prognosis." (PMID 34712733, 2021). "NEK2 (p<0.001) and TTK (p = 0.002) expression in the noninvolved lung tissue was also associated with a 3-fold increased risk of mortality from lung adenocarcinoma in smokers." (PMID 18297132, 2008).
glioblastoma (9 papers, 2019 to 2025). The most malignant astrocytic tumor (WHO grade IV). "In glioblastoma, NEK2 increases the stability and activity of NIK through phosphorylation, thereby activating non-classical NF-κB signaling and promoting tumor progression." (PMID 38503948, 2025). "The researchers showed that miR-128 was clearly associated with NEK2 using a dual luciferase reporter gene assay, and additional investigations showed that upregulation of NEK2 partially restored the effect of miR-128 on glioblastoma cell death." (PMID 36793341, 2022). "One study on glioblastoma showed that Nek2 protects EZH2 from ubiquitination-dependent protein degradation and its expression was found to be increased in recurrent tumors." (PMID 31319849, 2019). "Another group revealed the specific relationship between NEK2 and glioblastoma multiforme (GBM), also known as glioblastoma or grade IV astrocytoma." (PMID 32294979, 2020).
colon cancer (7 papers, 2020 to 2025). "In conclusion, the current study elucidated a novel molecular mechanism by which NEK2 regulates the metastatic behaviors of colon cancer cells by activating Rho GTPases through phosphorylating RhoGDI1." (PMID 39768163, 2024). "Consistent with these, NEK2 overexpression and knockdown experiments demonstrated that NEK2 promoted the proliferation, migration and invasion of colon cancer cells." (PMID 39768163, 2024). "Given that the activity of Rho GTPases is crucial for cancer cell proliferation and motility, and NEK2 enhanced the activity of RhoA and Rac1, we investigated the impact of NEK2 on the proliferation and metastatic behavior of colon cancer cells." (PMID 39768163, 2024). "Western analysis indicated that NEK2 is abundantly expressed in most colon cancer cell lines, while it is weakly expressed in Ls174T, LoVo, and DLD-1 cells." (PMID 39768163, 2024). "They analyzed the level of NEK2 expression in 60 colon cancer samples, 30 paracancerous colon tissue samples and 10 normal colon tissue samples." (PMID 32294979, 2020). "Lu and colleagues (2015) demonstrated high levels of NEK2 in colon cancer tissue by comparing paracancerous and normal tissues." (PMID 32294979, 2020). "Targeting NEK2 may enhance tumor cell sensitivity to cisplatin in colon cancers." (PMID 40076620, 2025). "Meanwhile, Nek2 is reported to inhibit cancer cell proliferation and promote tumorigenesis and progression in HCC and colon cancer." (PMID 35820920, 2022).
lymphoma (7 papers, 2013 to 2026). A malignant (clonal) proliferation of B- lymphocytes or T- lymphocytes which involves the lymph nodes, bone marrow and/or extranodal sites. "Similar findings from other study indicate that aberrant expression and activity of NEK2 drive the progression and transformation of lymphomas that ultimately causes a more aggressive disease." (PMID 26320076, 2015). "NEK2 has been shown to be upregulated in cancers such as lymphoma, cholangiocarcinoma, breast, prostate and cervical." (PMID 30974831, 2019). "Nek2, a member of the serine-threonine kinase family, is a cell cycle dependent protein kinase that has been shown to be upregulated in cancers such as lymphoma, cholangiocarcinoma, breast, prostate and cervical." (PMID 29301506, 2018). "Finally, we demonstrate that NEK2 inhibition can sensitize lymphomas to chemotherapy, resulting in a synergistic effect on lymphoma cell death." (PMID 38592451, 2024). "Thus, the author speculated that abnormally high expression of NEK2 might drive lymphoma progression." (PMID 34168996, 2021). "NEK2 inhibition reduced the expression and activity of cellular drug resistance transporter proteins, including MRP1, leading to increased lymphoma cell chemosensitivity." (PMID 42133805, 2026). "Together, these data suggest that NEK2 inhibition via JH295 administration sensitizes PEL and other NHLs to rapamycin therapy and that these drugs act synergistically to increase lymphoma death." (PMID 38592451, 2024). "Together, these data suggest that NEK2 represents a potent target for the treatment of PEL, and that JH295 administration could potentially help overcome the problem of drug resistance in lymphoma therapy." (PMID 38592451, 2024). "Taken together, these data indicate that JH295 treatment can sensitize both viral and nonviral lymphomas to chemotherapeutics currently in clinical use, and that NEK2 inhibition represents a potent anti-PEL strategy as both a monotherapy and as part of a synergistic combination therapy." (PMID 38592451, 2024). "We show NEK2 is necessary for the growth and survival of EBV-positive NHL, and that NEK2 inhibition selectively kills lymphoma cells but not normal lymphocytes." (PMID 42133805, 2026).
diffuse large B-cell lymphoma (6 papers, 2014 to 2025). "Similar to other kinases that are involved in spindle assembly or duplication, overexpression of NEK2 has been reported in several neoplastic diseases, such as preinvasive and invasive breast carcinomas, lung adenocarcinomas, testicular seminomas, and diffuse large B cell lymphomas." (PMID 26320076, 2015). "In Diffuse large B-cell lymphoma (DLBCL), NEK2 can enhance the stability of PKM2 by binding and phosphorylating, promoting cell proliferation and glycolysis." (PMID 38503948, 2025). "Taken together, our present study uncovered NEK2 facilitates cell proliferation and glycolysis by regulating PKM2 level through phosphorylation in diffuse large B-cell lymphoma." (PMID 34168996, 2021). "The serine/threonine kinase NEK2 (NIMA-related kinase 2), a member of NIMA-related kinase (NEK) family that regulates cell cycle, is upregulated in a variety of malignancies, including diffuse large B-cell lymphoma." (PMID 34168996, 2021).
non-small cell lung carcinoma (6 papers, 2014 to 2025). A group of at least three distinct histological types of lung cancer, including non-small cell squamous cell carcinoma, adenocarcinoma, and large cell carcinoma. "Furthermore, reduced NEK2 expression was found to be associated with the inhibition of non-small cell lung cancer oncogenesis and spread." (PMID 37600577, 2023).
pancreatic ductal adenocarcinoma (6 papers, 2017 to 2022). An infiltrating adenocarcinoma that arises from the epithelial cells of the pancreas. "NEK2 is a well-recognized oncogene and a potent enhancer of PD-L1 in pancreatic ductal adenocarcinoma and the alteration of NEK2 orchestrated other phenotypes in migration, and chemoresistance." (PMID 35705994, 2022). "In patients with pancreatic ductal adenocarcinoma, high expression levels of NEK2 were substantially correlated with lymph node metastasis (p = 0.003) and tumor stage (p = 0.001)." (PMID 34072728, 2021).
lymph node metastasis (5 papers, 2014 to 2025). "NEK2 expression was found to be correlated with T stage and lymph node metastasis." (PMID 25202351, 2014). "We found that patients with high NEK2 and TUFT1 expression had a significantly high rate of lymph node metastasis, reflecting poor outcome." (PMID 41022752, 2025).
ciliopathy (4 papers, 2021 to 2025). A genetic disorder of the cellular cilia or the cilia anchoring structures, the basal bodies, or of ciliary function. "While it remains a highly attractive target for the development of anti-cancer therapeutics, several new roles of the Nek2 enzyme have recently emerged: these include drug resistance, bone, ciliopathies, immune and kidney diseases, and parasitic diseases such as malaria." (PMID 35056661, 2022). "In addition, NEK2-mediated activation of KIF24 is required for ciliary disassembly and incorrect functioning of NEK2 is related to the ciliopathy retinitis pigmentosa (RP)." (PMID 33860332, 2021).
clear cell renal cell carcinoma (4 papers, 2020 to 2025). "NEK2 is associated with poor prognosis of clear cell renal cell carcinoma and promotes tumor cell growth and metastasis." (PMID 40385396, 2025). "Previous studies have revealed the critical functions of NEK2 in controlling the cell cycle which is linked to poor prognosis in multiple tumor types, but less research has been devoted to clear cell renal cell carcinoma (ccRCC)." (PMID 38758909, 2024).
esophageal squamous cell carcinoma (4 papers, 2023 to 2025). Esophageal squamous cell carcinoma (ESCC) is a type of esophageal carcinoma (EC) that can affect any part of the esophagus, but is usually located in the upper or middle third. "The NEK2 mRNA and protein levels are upregulated in esophageal squamous cell carcinoma (ESCC)." (PMID 40076620, 2025). "In addition, NEK2 stabilizes Yes1 associated transcriptional regulator (YAP1) via phosphorylation at Thr-143, promoting Esophageal Squamous Cell Carcinoma (ESCC) migration and proliferation." (PMID 38795132, 2024). "Hence, this study aimed to explore the molecular function of NEK2 in esophageal squamous cell carcinoma (ESCC)." (PMID 37233832, 2023).
melanoma (4 papers, 2017 to 2024). A malignant, usually aggressive tumor composed of atypical, neoplastic melanocytes. "Depletion of NEK2 in 92.1 uveal melanoma cells resulted in significant increase in multipolar mitotic spindles, in contrast to control cells in which most of the spindles were bipolar." (PMID 38182898, 2024). "Melanoma which is considered a very aggressive tumor that affects the melanocytes, is also related to NEK2." (PMID 32294979, 2020). "High expression of metastasis-associated CD271-responsive genes NEK2, RAD51AP1, TOP2A and NGF in drug-resistant MeWo cells and their drug-dependent regulation, may have consequences for the priming of melanoma cells for metastasis." (PMID 28112719, 2017). "Among the genes predicting either melanoma metastasis or relapse were hyaluronan mediated motility receptor (HMMR), NIMA related kinase 2 (NEK2), and DNA-repair genes." (PMID 32878000, 2020). "Further, we identified 110 CD271-responsive genes predominantly expressed in melanoma metastases, among them were NEK2, TOP2A and RAD51AP1 as potential drivers of melanoma metastasis." (PMID 28112719, 2017). "In addition to NEK2, a study in the literature showed that NEK10 is also related to melanoma." (PMID 32294979, 2020).
nasopharyngeal carcinoma (4 papers, 2019 to 2024). A carcinoma arising from the nasopharyngeal epithelium. "Nasopharyngeal carcinoma (NPC), also related to NEK2, affects the nasopharynx epithelium." (PMID 32294979, 2020).
breast tumors (3 papers, 2011 to 2022). "Also, E2F1, E2F2, E2F3, Mps1/TTK, BubR1, NDC80 (HEC1), Nek2, and Sgo1 significantly co-overexpress in breast tumors." (PMID 29100415, 2017). "It is noteworthy that the other two genes (NEK2 and PLK), that showed similar mRNA levels in amplified and unamplified breast tumors, are located on chromosome arms (1q and 16p, respectively) showing polysomy and no DNA amplification in breast tumors." (PMID 21352579, 2011). "Five of these genes (NEK2, PLK, BIRC5, TPX2 and AURKA) displayed DNA amplification (or polysomy) in more than 30% of breast tumors." (PMID 21352579, 2011). "NHW women with Her2 + breast tumors significantly overexpress TTK, TBK1, Nek2, BUB1, and SGOI." (PMID 36494865, 2022). "All the mitotic regulators above, including Nek2 and TTK, are also overexpressed in non-classified breast tumors." (PMID 36494865, 2022).
small cell lung carcinoma (3 papers, 2020 to 2023). Small cell lung cancer (SCLC) is a highly aggressive malignant neoplasm, accounting for 10-15% of lung cancer cases, characterized byrapid growth, and early metastasis. "The aim of this pilot study was to determine mRNA and protein levels of NEK2, PIM1, and PIM3 in a group of 49 patients with BP-NENs: 11 typical carcinoids, 5 atypical carcinoids, 11 large cell neuroendocrine carcinomas, 22 small cell lung carcinomas (SCLC)." (PMID 32504181, 2020).
cutaneous melanoma (2 papers, 2024). A primary melanoma arising from atypical melanocytes in the skin. "NEK2 is dysregulated in diverse tumor types and upregulated mostly, except pheochromocytoma and paraganglioma, skin cutaneous melanoma and thymoma." (PMID 38758909, 2024).